PAX2 (paired box 2)
Diseases named in the same sentence as PAX2 in open-access papers (continued):
Sharing a sentence is not in itself a finding about the gene and the disease.
cystic kidneys (4 papers, 2017 to 2025). "Mutations of PAX2 seem to be more frequently associated with renal hypodyplasia, while mutations in HNF1β are more frequently associated with cystic kidneys." (PMID 28398236, 2017). "In one such case, a nephrectomy specimen of the right-sided hypodysplastic cystic kidney was available, and hematoxylin-eosin and PAX2 staining showed very little morphologically normal kidney tissue indicating severe dysplasia." (PMID 41278353, 2025). "A recent study that investigated PAX2 gene mutations in 457 Japanese patients diagnosed with CAKUTs, cystic kidneys or renal dysfunction of unknown origin with or without any ocular abnormalities observed the presence of pathogenic PAX2 variants in 38 cases (6.5%)." (PMID 37628926, 2023).
Glomerular Disease (4 papers, 2014 to 2025). "Taken together, these results demonstrate that remission or progression of glomerular disorders after podocyte injury depends upon a balance between an efficient and dysfunctional differentiation of PAX2+ progenitors into podocytes." (PMID 26235895, 2015). "However, in experimental glomerular disease, the number of PAX2 positive cells in the tuft increased, but was significantly higher in SM22α -/- mice compared to SM22α +/+ mice at day 14 (303.13 ± 41.07 vs. 576.51 ± 55.52; P <0.01)." (PMID 25376243, 2014).
kidney malformations (4 papers, 2018 to 2024). "Many studies suggest that CNVs contribute to the etiology of RHD and implicate the genes within the CNV loci (e.g., PAX2, HNF1B, KIF26B, which are associated with kidney defects), that are detected in up to 10% of individuals with kidney malformations." (PMID 32211073, 2020). "As the hPSCs differentiate toward kidney progenitors in vitro, they expressed the transcription factors PAX2 and SALL1, respectively mutated in the human renal coloboma and Townes-Brocks syndromes featuring kidney malformations." (PMID 29429961, 2018). "In the last 28 years, many cohort studies and case reports highlighted PAX2’s involvement in a large spectrum of kidney malformations and diseases, with or without eye abnormalities, defining the phenotypes associated with PAX2 variants as “PAX2-related disorders”." (PMID 36835576, 2023).
medulloblastoma (4 papers, 2013 to 2021). A malignant, invasive embryonal neoplasm arising from the cerebellum. "Likewise, functional data showing overexpression of PAX2 in hindbrain and cerebellar development as a driver of medulloblastoma has implicated PAX2 as a proto-oncogene." (PMID 34012965, 2021).
nephrotic syndrome (4 papers, 2019 to 2023). A collection of symptoms that include severe edema, proteinuria, and hypoalbuminemia; it is indicative of renal dysfunction. "Other studies on mice have also shown the importance of PAX2 in normal kidney development and the repercussions of PAX2 overexpression, which is incompatible with normal kidney formation and results in kidney abnormalities that are comparable to human nephrotic syndromes." (PMID 37628926, 2023). "A recent article reported concomitant identical heterozygous mutations in PAX2 (c.491C>A, p.Thr164Asn) and MYO1E genes in a pair of twin girls with steroid-dependent nephrotic syndrome and a similar phenotype but no extrarenal signs." (PMID 37628926, 2023). "Mutations in the protein coding paired box gene 2 (PAX2) and in the non-muscle class I myosin, myosin 1E, (MYO1E) have been implicated in the development of steroid-resistant nephrotic syndrome." (PMID 35574290, 2022).
ovarian tumors (4 papers, 2012 to 2023). "As in women, PAX2 expression has also been reported in oviduct of normal hens as well as in ovarian tumors." (PMID 34314463, 2021). "PAX2 has been reported to be expressed in prostate cancer and in both high- and low-grade ovarian tumors in women." (PMID 34314463, 2021). "We used seven histologic markers (PAX2, PAX8, ER, PR, WT1, CK20 and CDX2) commonly expressed in other types of ovarian tumors such as serous, mucinous or endometrioid." (PMID 35387670, 2022). "In ovarian tumors, PAX2 is detected in clear cell and mucinous tumors, but absent in most endometrioid tumors, while PAX8 shows high expression in clear cell and endometrioid tumors and reduced expression in mucinous tumors." (PMID 35387670, 2022).
pancreatic cancer (4 papers, 2009 to 2026). "Additionally, it was found that PAX2 silencing in pancreatic cancer cells increases susceptibility towards known clinical agents." (PMID 31622355, 2019). "In addition, it was also found that PAX2 transcriptional factor can bind to the promoter of previously reported transmembrane-domain family TM4SF1, a gene that played a role in gemcitabine resistant pancreatic cancer." (PMID 31622355, 2019).
renal agenesis (4 papers, 2012 to 2025). Renal agenesis (RA) is a form of renal tract malformation characterized by the complete absence of development of one or both kidneys (unilateral RA or bilateral RA respectively), accompanied by absent ureter(s). "This mutation may disrupt the transcription of WNT11 and PAX2, thereby affecting the development and function of fetal kidney ureteric bud cells, ultimately resulting in renal agenesis." (PMID 40483479, 2025). "While complete loss of Pax2 expression results in renal agenesis, Pax2+/− kidneys are hypoplastic." (PMID 22984579, 2012). "The homozygous inactivation of PAX2 leads to bilateral renal agenesis, and this is incompatible with life." (PMID 38139322, 2023). "Mutations in EYA1, PAX2, SIX1, or SIX2, have been found in a subset of human patients with renal agenesis or hypoplasia." (PMID 27442016, 2016). "Therefore, the SALL4 mutant protein may cause renal agenesis by failing to transcriptionally activate WNT11 and PAX2, thus affecting kidney development." (PMID 40483479, 2025). "The Eya1, Pax2, and Six1 transcription factors are each required for activation and/or maintenance of Gdnf expression in the metanephric mesenchyme and mice lacking any one of them die perinatally with bilateral renal agenesis." (PMID 27442016, 2016).
renal dysplasia (4 papers, 2017 to 2024). Renal dysplasia is a form of renal malformation in which the kidney(s) are present but their development is abnormal and incomplete. "It was found that Pax2 and Pax8 mainly contribute to the development of pronephros and mesonephros and that Pax2 and Pax8 double-null mice fail to generate the nephric duct and have renal dysplasia." (PMID 34205452, 2021).
acute lymphoblastic leukaemia (3 papers, 2011 to 2025). "For instance, increasing the expression of SMN2 may have clinical utility in patients with spinal muscle atrophy owing to SMN1 mutations, and increased expression of PAX2 or PAX8 may be of interest in patients with predisposition to acute lymphoblastic leukemia due to PAX5 mutations." (PMID 34818036, 2021). "Under hyperosmolar conditions, NFAT5 drives the activation of paired box 2 (PAX2) in coordination with PAX5, in pre-B acute lymphoblastic leukaemia cells." (PMID 40421201, 2025).
autism (3 papers, 2021 to 2025). Persistent deficits in social interaction and communication and interaction as well as a markedly restricted repertoire of activity and interest as well as repetitive patterns of behavior. "In the Bdnf Pax2 knockout mouse model of autism, impaired maturation of the high-spontaneous rate auditory nerve fibers alter spike synchrony and affect cortical auditory processing." (PMID 40758713, 2025). "BDNF in Pax2-lineage descendants in lower brain regions should thus be considered as a novel candidate for contributing to the development of brain disorders, including autism." (PMID 33841098, 2021). "BDNF in Pax2-lineage descendants in lower brainstem regions may thus be involved in the disturbed migration of GABAergic INs which may contribute to the pathophysiology of multiple psychiatric disorders, including autism." (PMID 33841098, 2021).
hearing loss (3 papers, 2021 to 2025). "Developmental abnormalities of these regions are directly associated with congenital hearing loss, implying that PAX2 is a relevant putative gene involved in congenital pediatric deafness." (PMID 34912812, 2021).
leukemia (3 papers, 2019 to 2023). A malignant (clonal) hematologic disorder, involving hematopoietic stem cells and characterized by the presence of primitive or atypical myeloid or lymphoid cells in the bone marrow and the blood. "Among the negatively associated genes, several genes including PAX2, IL2RA, SOX11, and PAK7 played as oncogenes in leukemia." (PMID 32209730, 2020).
lung cancer (3 papers, 2012 to 2021). A malignant neoplasm involving the lung. "Pax2 was moderately expressed in the tested cell lines, except for A549 cells derived from lung cancer tissue." (PMID 34824296, 2021). "Matrine can inhibit EMT and inhibit metastasis in nonsmall cell lung cancer by inhibiting the expression of paired box 2 (PAX2)." (PMID 32477114, 2020).
mucinous tumors (3 papers, 2021 to 2023). "Recently, new Müllerian markers (PAX2 and PAX8) are reported as useful markers to differentiate Müllerian mucinous tumors from non- Müllerian tumors." (PMID 35387670, 2022). "Mucinous tumors and BTs tend to be negative for PAX-2 and PAX-8, two highly sensitive mullerian epithelial markers that are often positive in other ovarian epithelial neoplasms." (PMID 36810485, 2023). "PAX2 has been shown to be expressed in normal adult female reproductive tissues, be absent in ~85% of HGSC, and be expressed in clear cell and mucinous tumors." (PMID 34314463, 2021).
multicystic dysplastic kidney (3 papers, 2011 to 2025). Multicystic dysplastic kidney (MCDK) is a congenital anomaly of the kidney and urinary tract (CAKUT) in which one or both kidneys (unilateral or bilateral MCDK respectively) are large, distended by multiple cysts, and non-functional. "The overexpression of PAX2 gene can inhibit nephron progenitor cell differentiation, resulting in multicystic dysplastic kidneys, which are filled with cysts and lack normal structures." (PMID 40282888, 2025). "Renal phenotypes of mutations in HNF1B, PAX2, and EYA1 were bilateral renal hypodysplasia or unilateral renal hypodysplasia with contralateral multicystic dysplastic kidney." (PMID 32164334, 2020). "The molecular events involved in multicystic dysplastic kidneys, in general, remain to be elucidated, though studies have suggested involvement of WNT-1, FGFR3, and PAX2." (PMID 21995344, 2011).
Retinal coloboma (3 papers, 2007 to 2014). A notch or cleft of the retina or choroid, located vertically below the optic disc. "Analysis of PAX2, a cause of optic disc and retinal coloboma (OMIM 120330), has identified roles in both patterning the optic stalk/neural retina boundary together with PAX6 (i), and for fissure closure and correct development of the optic disc (v and vi)." (PMID 24412933, 2014).
serous carcinomas (3 papers, 2013 to 2024). "However, recent studies indicated that loss of PAX2 expression correlates with the development of serous carcinoma in the fallopian tube." (PMID 23502471, 2013). "PAX2 showed normal expression in almost all MA versus 8.0% of high‐grade serous carcinomas and 14.6% of initial EC." (PMID 38970797, 2024). "We corroborated those findings using publicly available data comprising of several RNAseq samples from normal and cancerous endometrial tissue, in which expression of PAX2 was significantly reduced in tumor samples (Endometrioid and Serous adenocarcinomas) compared to normal tissue." (PMID 35018885, 2022).
urogenital cancers (3 papers, 2008 to 2023). "By attaching to this protein’s DNA binding site, EG1 can phenocopy a PAX2 mutation to prevent PAX2–DNA interactions in vitro and in ex vivo kidney organ cultures; consequently, this could be beneficial in the future for the treatment of many urogenital cancers and renal malignancies." (PMID 37628926, 2023). "Three novel missense variants which were absent in Gnomad were identified in PAX2 (p.Ser305Leu in child with unilateral hypodysplastic kidney), SALL1 (p.Phe447Tyr in patient with bilateral VUR) and RET genes (p.Gly533Ser in child with unilateral vesico-ureteric junction obstruction)." (PMID 34979951, 2022).
Anxiety (2 papers, 2021 to 2024). Intense feelings of nervousness, tension, or panic often arise in response to interpersonal stresses. "Heterozygous Pax2 mice, exhibited an autistic-like pattern, evidenced through increased self-grooming and anxiety, although normal social behavior and working memory." (PMID 33841098, 2021). "Therefore, it is reasonable to speculate that increased self‐grooming will result in less anxiety in Nestin‐Pax2 mice." (PMID 37786962, 2024).
bladder cancer (2 papers, 2019 to 2023). "Moderate mRNA expression and the detectable protein expression of PAX2 were observed in bladder cancer EJ cells." (PMID 37627900, 2023). "The knockdown of PAX2 inhibited and induced apoptosis in the EJ cells as compared to the control cells, thus suggesting that PAX2 is essential for the proliferation and survival of bladder cancer cells." (PMID 37627900, 2023).
BOR syndrome (2 papers, 2020 to 2023). "Mutations in PAX2 and EYA1 cause the autosomal dominant disorders renal coloboma syndrome and BOR syndrome, respectively." (PMID 32164334, 2020).
breast tumors (2 papers, 2011 to 2017). "PAX2 expression was also detected in breast tumours: although a relatively small number of samples have been analyzed to date, PAX2 expression can equally be found in different types of tumours." (PMID 22168360, 2011). "On the other hand, a differential regulation of PAX2 activation has been evidenced between breast tumour subtypes: nuclear localization of PAX2 is frequent in luminal tumours and infrequent in non-luminal tumours." (PMID 22168360, 2011).
CHARGE syndrome (2 papers, 2006 to 2011). CHARGE syndrome is a multiple congenital anomaly syndrome characterized by the variable combination of multiple anomalies, mainly Coloboma; Choanal atresia/stenosis; Cranial nerve dysfunction; Characteristic ear anomalies (known as the major 4 C's). "Therefore, PAX2 was further analyzed in 34 patients fulfilling the diagnostic criteria of the CHARGE syndrome, though no deletions or nucleotide variations of the coding sequence were detected, suggesting that mutations of the PAX2 gene was not a cause of the CHARGE." (PMID 21995344, 2011).
ciliopathies (2 papers, 2021 to 2025). "In this cohort, two patients carrying PAX2 gene variants were identified: one with a clinical suspicion of nephronophthisis-related ciliopathy and the other with an unspecified glomerular kidney disease." (PMID 40282888, 2025).
clear cell ovarian cancer (2 papers, 2010 to 2013). "The effect of PAX2 knockdown on cell proliferation was significant (p < 0.05) in the clear cell ovarian cancer cell line TOV21G." (PMID 23502471, 2013). "Nevertheless, Pax-2 expression was noted in 42.9% of clear cell ovarian carcinomas, and no endometrial clear cell carcinoma was included in this study." (PMID 20454689, 2010).
colorectal carcinoma (2 papers, 2021 to 2023). A malignant epithelial neoplasm that arises from the colon or rectum and invades through the muscularis mucosa into the submucosa. "We used RT-qPCR to determine the relative expression levels of four paired box (PAX) genes which are most likely to encode binding targets for EG1 in colorectal carcinoma cells (PAX2, PAX5, PAX6, PAX8)." (PMID 34722257, 2021). "It was proven recently that PAX2 expression promotes angiogenesis in ovarian and colorectal carcinoma cell lines and also the formation of liver metastasis in colorectal carcinoma, suggesting its important role in oncogenesis." (PMID 37628926, 2023).
deafness (2 papers, 2011 to 2025). An inherited or acquired condition characterized by the complete loss of the ability to hear from one or both ears. "It is therefore possible that Jip1 mutations in humans might affect Pax2 function and consequently lead to deafness." (PMID 40213817, 2025). "For example, it delays disease onset and extends the survival in the amyotrophic lateral sclerosis transgenic mouse model, it rescues renal hypoplasia in paired box 2 (Pax2)-deficient mice and promotes cochlear hair cell survival in the Pou4f3 mouse model of deafness." (PMID 21677791, 2011).
Endometrial Intraepithelial Neoplasia (2 papers, 2022 to 2025). A premalignant neoplastic process that affects the endometrial epithelium and glands. "The abnormal loss of nuclear Pax-2 expression is observed in approximately 70–80% of cases of EC and atypical hyperplasia/endometrial intraepithelial neoplasia (AH/EIN)." (PMID 40357279, 2025). "Numerous studies have validated the diagnostic value of Pax-2 loss in identifying atypical hyperplasia/endometrial intraepithelial neoplasia (AH/EIN)." (PMID 40357279, 2025). "Loss of PAX2 expression has been implicated in the development of endometrial intraepithelial neoplasia (EIN) and PAX2 is potentially useful in the diagnostic of difficult EIN cases (e.g. where there is no ‘normal’ tissue available to act as an internal control when assessing nuclear morphology)." (PMID 35018885, 2022).
endometrial polyp (2 papers, 2024 to 2025). A benign nodular lesion protruding above the surface of the endometrium. "However, the loss is typically focal and does not exceed 5% of the entire specimen, except in cases of endometrial polyps, where approximately 10–20% of cases show more widespread PAX2 loss." (PMID 38539494, 2024). "The expression characteristics of PAX2 and PTEN in interval endometrium and secretory endometrium were similar to those of proliferative endometrium and endometrial polyps." (PMID 40361423, 2025). "The prevalence of PAX2 and PTEN aberrancy in secretory AH/EIN was comparable to that reported in previous studies of non-secretory AH/EIN and AH/EIN within endometrial polyps." (PMID 40361423, 2025).
endometrial tumor (2 papers, 2022 to 2025). "Taken together, these complementary sets of experiments provide preliminary evidence for PAX2 as a significant endometrial tumor suppressor, whose inactivation promotes EC cell mitotic proliferation." (PMID 40829174, 2025). "Our findings suggest that endometrial response to progestins in differentiated endometrial tumor cells results in part from binding of PR together with PAX2 to accessible chromatin regions." (PMID 35018885, 2022). "Our mouse models establish PAX2 as an in vivo endometrial tumor suppressor synergizing with PTEN." (PMID 40829174, 2025). "Mouse and human preclinical models established PAX2 as a potent endometrial tumor suppressor." (PMID 40829174, 2025).
endometrioid adenocarcinomas of the ovary (2 papers, 2013 to 2025). "Marker aberrance was most frequent in endometrioid adenocarcinomas of the ovary, with PAX2 aberrance in 93.1% of cases, followed by PTEN (27.6%) and β-catenin (48.3%)." (PMID 39078313, 2025).